IL10 (interleukin 10)
Diseases named in the same sentence as IL10 in open-access papers (continued):
Sharing a sentence is not in itself a finding about the gene and the disease.
endometritis (26 papers, 2012 to 2025). An acute or chronic, usually bacterial infectious process affecting the endometrium. "The nucleotide sequences of healthy and endometritis-affected cows were found to differ by using PCR-DNA sequencing for the IL10 gene." (PMID 40711280, 2025). "The results revealed a significant increase in the expression levels of inflammatory-related factors TNF-α (p < 0.001), IL-8 (p < 0.001), and IL-10 (p < 0.001) in the uterus with endometritis." (PMID 38473153, 2024). "The results showed that the IL-6, IL-1β, and TNF-α were decreased, and the IL-10 was increased in mice with endometritis treated with naringin." (PMID 39234103, 2024). "High expression of IL-8 and IL-10 in endometritis groups proves that it is consistent with the pathological examination and cytological examination." (PMID 36139304, 2022). "Previous studies have shown that endometrial expression of IL-10 increases in experimentally induced endometritis in mares, contributing to the decrease of the expression of pro-inflammatory cytokines." (PMID 34944269, 2021). "The serum levels of TNF-α and IL-6 (p < 0.01) as well as Hp and SAA (p < 0.001) were higher in cows with subclinical endometritis, while the levels of IL-10 were lower (p < 0.001) compared to the uterine washings." (PMID 25846950, 2015). "The uterine washings in cows with subclinical endometritis had significantly higher levels of IL-6, IL-10, and Hp compared to the healthy group (p < 0.001)." (PMID 25846950, 2015). "The listed uterine washing tests have shown only slight changes in the concentration of TNF-α, IL-6 and IL-10 in cows with subclinical endometritis." (PMID 25846950, 2015). "However, in studies of LPS-induced endometritis in cattle, E. coli increased the expression of Th2 factor IL-10." (PMID 40564264, 2025). "Therefore, the behavior of the IL-10 gene and its expression needs to be deeply explored in order to identify its role in endometritis-infected buffaloes." (PMID 39858163, 2025). "It is possible that TNF-α, IL-1β, IL-4 and IL-10 significantly generated during endometritis, by increasing the viability of stromal cells, may affect the regeneration of endometrial cells damaged by inflammation." (PMID 39843578, 2025). "The IL10 gene was expressed at much lower levels in cows suffering from endometritis." (PMID 40711280, 2025). "In blood, serum, or plasma, IL-10 has been measured using single-plex ELISA in cows across several systemic contexts, including the prediction of postpartum reproductive disorders, paratuberculosis status, and clinical or subclinical endometritis windows." (PMID 41226434, 2025). "The reason why there is a noticeable rise in the number of uterine washings performed on cows with subclinical endometritis could be because IL-10, which is produced by different types of T-cells, has anti-inflammatory properties." (PMID 40005882, 2025). "Interestingly, signs indicating that biofilms can modulate local inflammatory responses have also been observed, e.g., in equine endometritis where the increased production of anti-inflammatory Interleukin 10 was found in areas surrounding the biofilms." (PMID 36985183, 2023). "In addition, we have also demonstrated that cows with endometritis had a 2-fold higher concentration of IL-10 in uterine washings than in blood serum." (PMID 25846950, 2015). "However, uterine washings demonstrated higher levels of IL-6, IL-10 and HP in cows with subclinical endometritis than healthy cows." (PMID 25846950, 2015). "Previous studies by Fumuso and co-workers showed that mares susceptible to persistent endometritis had significant upregulated cellular immune response (IL-1β, IL-6, TNF-α and IL-8) and down-regulated anti-inflammatory activity (IL-10) compared to resistant mares at estrous baseline levels." (PMID 22458733, 2012).
endometritis (continued). "Hence, we concluded that ICA might express its protective effect by attenuation of the production of IL-1β, IL-6, and TNF-α as well as boosting the production of IL-10 in LPS-induced endometritis." (PMID 36142129, 2022). "Interestingly, high levels of IL-10 were observed in cows with subclinical endometritis, which might contribute to the weakening of uterine resistance to pathogens and lead to the persistence of the inflammation, postpartum." (PMID 30646595, 2019). "Concerning the APPs and cytokines, the serum levels of Hp, SAA, Cp, IL-6, IL-10 and TNF-α were significantly (P˂0.05) increased in buffalo–cows with endometritis compared to healthy ones." (PMID 38459095, 2024). "The serum levels of Hp, SAA, Cp, IL-6, IL-10, TNF-α, NO and MDA were significantly (P˂0.05) increased, along with reduction of CAT, GPx, SOD and TAC in buffalo–cows with endometritis compared to healthy ones." (PMID 38459095, 2024). "For each gene examined in the endometritis-affected cows, TLR4 had the highest potential mRNA level (2.51 ± 0.11); IL10 had the lowest potential level (0.31 ± 0.06)." (PMID 37368756, 2023). "The IL10, ATOX1, and GST genes were expressed at significantly lower amounts in endometritis-affected cows according to the molecular changes." (PMID 37368756, 2023). "The IL10, ATOX1, and GST genes were expressed at substantially lower levels in endometritis-affected cows." (PMID 37368756, 2023). "Using PCR-DNA sequencing for the immunological (TLR4, IL10, TLR7, NCF4, TNF-α, and LITAF) genes, there were changes in the nucleotide sequence between endometritis-affected cows and healthy ones." (PMID 37756095, 2023). "qRT-PCR results showed that the endometritis tissues secreted the proinflammatory cytokines IL-1β, IL-6, and TNF-α, but there was a decreased secretion of IL-10, an anti-inflammatory mediator." (PMID 34504639, 2021). "In agreement with our results, IL-1, IL-6, IL-10, and TNF have been found to be significantly downregulated in a mare endometritis model with chronic pathological endometrial changes, including fibrosis, after mesenchymal stem cell treatment." (PMID 29954457, 2018). "Supporting current results, researchers found significant increase in IL-1, IL-6, IL-10, and TNF in a mare model of endometritis with chronic pathological endometrial changes including fibrosis." (PMID 28883083, 2017). "The aim of the study was to evaluate the concentrations of proinflammatory cytokines: TNF-α and IL-6, anti-inflammatory cytokine IL-10, and APPs - Hp and SAA, in the serum and uterine washings of cows with subclinical endometritis and healthy animals." (PMID 25846950, 2015). "The results show that the levels of TNF-α (p < 0.01), IL-6, IL-10 as well as SAA and Hp were significantly higher in the serum of cows with subclinical endometritis compared to the controls (p < 0.001)." (PMID 25846950, 2015). "Nucleotide sequence variations between healthy and endometritis-affected cows were revealed using PCR-DNA sequencing for immune (TLR4, TLR7, TNF-α, IL10, NCF4, and LITAF), antioxidant (ATOX1, GST, and OXSR1), and erythritol-related (TKT, RPIA, and AMPD1) genes were reported by44." (PMID 38459095, 2024). "Single nucleotide variants (SNPs) in the genes were discovered using PCR-DNA sequencing for immune (TLR4, TLR7, TNF-α, IL10, NCF4, and LITAF), antioxidant (ATOX1, GST, and OXSR1), and erythritol-related (TKT, RPIA, and AMPD1) genes found in resistant and endometritis-infected Holstein dairy cows." (PMID 37368756, 2023). "Nucleotide sequence variations between healthy and endometritis-affected cows were revealed using PCR-DNA sequencing for immune (TLR4, TLR7, TNF-α, IL10, NCF4, and LITAF), antioxidant (ATOX1, GST, and OXSR1), and erythritol-related (TKT, RPIA, and AMPD1) genes." (PMID 37368756, 2023).
endometritis (continued). "Molecular genetic analyses of the immunological (TLR4, TLR7, TNF-α, IL10, NCF4, and LITAF), antioxidant (ATOX1, GST, and OXSR1), and erythritol-related (TKT, RPIA, and AMPD1) genes comparing healthy and endometritis cows found differences in nucleotide sequence and transcript levels." (PMID 37368756, 2023). "The immune (TLR4, TLR7, TNF-α, IL10, NCF4, and LITAF), antioxidant (ATOX1, GST, and OXSR1), and erythritol-related (TKT, RPIA, and AMPD1) genes in endometritis-affected and healthy Holstein dairy cows were characterized in this research using a PCR-DNA sequencing technique." (PMID 37368756, 2023). "The data shows that the levels of TNF-α (p < 0.01), IL-6, IL-10 (68.73 ± 12.15 pg/ml), as well as acute phase proteins (SAA and Hp) in the serum of cows with subclinical endometritis were significantly higher compared to healthy cows (IL-10 53.59 ± 3.19 pg/ml) (p < 0.001)." (PMID 25846950, 2015). "We have shown in our study significantly higher levels of IL-6, IL-10, and Hp in uterine washings of cows with endometritis compared to cows without the disease." (PMID 25846950, 2015).
gout (26 papers, 2017 to 2025). A condition characterized by painful swelling of the joints, which is caused by deposition of urate crystals. "The results showed that low expression of key genes CXCL8, PTGS2 and IL10 were risk factors for gout." (PMID 40606658, 2025). "In addition, IL-6 was associated with inflammatory activity in gout, the presence of tophi and articular deformities and IL-10 down-regulated the inflammatory responses in gout through inhibition of TNF-α, MIP-1α, and MIP-1β in MSU crystal–stimulated cells." (PMID 38711064, 2024). "In the maintenance stage of inflammation, polarized M2 macrophages can secrete anti-inflammatory cytokines including TGF-β and IL-10, which may relieve gout inflammation; however, the mechanism underlying spontaneous resolution has not been clearly elucidated." (PMID 35449811, 2022). "This study systematically elucidated the pivotal roles of CXCL8, PTGS2, and IL10 in gout pathogenesis, providing valuable molecular targets for therapeutic development." (PMID 40606658, 2025). "CXCL8 and PTGS2 were predominantly expressed in T/NK cells and myeloid cells, while IL10 was mainly expressed in myeloid cells, with all key genes showing elevated expression in the gout group." (PMID 40606658, 2025). "Second, both Bics changed inflamed synovial cells from both RA and gout into IL-10-secreting cells, with a plateau observed above 200 nM." (PMID 38601165, 2024). "Treg cells have been demonstrated to lessen gout-related immune response and bone damage by secreting cytokines immunosuppressive such as IL-10 and transforming growth factor (TGF)-β." (PMID 38240927, 2024). "Cytokine levels, including IFN-γ, TNF-α, IL-2, IL-4, IL-6, IL-10 and IL-17, were detected in early-onset gout, late-onset gout and HCs." (PMID 38240927, 2024). "In our study, plasma cytokines including IL-1β, IL-6 and IL-10 were significantly higher in RA than OA, while TNFα was higher in gout than RA." (PMID 37202736, 2023). "Compared with the CON group, the content of IL-8, TNF-α, IL-1β, NF-κB, UA in serum and ESR from the MOD group were increased, and IL-10 content were decreased indicating that the acute gouty arthritis model of animals was successfully built." (PMID 36090056, 2022). "The theory of the premutation leading to immune dysfunction and gout is supported by the observation that the peripheral blood of males with FXTAS have elevated IL‐10 a proinflammatory cytokine which is a mediator in the development of gout." (PMID 36447664, 2022). "On the other hand, IL-5, IL-10, and eotaxin were lower in patients with acute gout inflammation, which can be explained by their role in inhibiting inflammation (IL-10) or eosinophilic inflammation (IL-5, eotaxin)." (PMID 31739430, 2019). "IL-5, IL-10, and IL-12 levels gradually decreased from control, subsequently hypouricemia, and gout to gout attack group." (PMID 31739430, 2019). "Our results regarding IL-10 levels are supported by similar findings of circulating IL-10 in a Netherlands gouty arthritis study cohort and in New Zealand patients with intercritical gout study." (PMID 31739430, 2019). "Because the MSU intra-articular injection significantly increased the levels of MCP-1 as well as 6-Keto-PGF1α and depressed the level of IL-10 in the serum of rats, we believe that this rat model provides a reasonable representation of acute gout in humans." (PMID 31622116, 2019). "As an anti-inflammatory cytokine, IL-10 activates macrophages to turn off, damaging the immune system during the process of gout." (PMID 28929115, 2017). "We found that IL-10 production from monocytes/macrophages of gout patients was significantly higher compared to the production in RA patients." (PMID 29056937, 2017). "Additionally, gout patients had significantly higher cytokines levels (including IL-2, IL-4, IL-6, IL-10, IL-17, IFN-γ, and TNF-α) than HCs; IL-2 levels were positively correlated with Treg cells and negatively correlated with ESR." (PMID 38240927, 2024).
gout (continued). "It has also been reported that the elevation of anti-inflammatory cytokine IL-10 may be involved in the self-regulation of acute inflammatory immunity in gout patients." (PMID 39130631, 2024). "To further investigate the secretion of cytokines under various Teff/Treg ratios, we found that both the proinflammatory cytokine IFN-γ and the antiinflammatory cytokine IL-10 exhibited higher concentrations in the culture supernatant during gout flare compared with gout remission." (PMID 38063198, 2023). "Among these, pergolide exhibited the highest binding affinity with key gene-encoded proteins, suggesting potential therapeutic effects against gout through targeting CXCL8, PTGS2, and IL10." (PMID 40606658, 2025). "To explore the role of TLRs and key cytokines in gout pathogenesis, we reanalyzed a publicly available dataset, focusing on the expression of TLRs, IL-1β, IL-18, TNF-α, IL-10, and TGF-β in patients experiencing gout flare versus remission." (PMID 41583461, 2025). "Among 329 gout-related genes identified, CXCL8, PTGS2, and IL10 emerged as key regulators involved in cell-cell adhesion, leukocyte activation, and NF-κB signaling." (PMID 40606658, 2025). "The correlation analysis in gout patients showed that there were significantly negative correlations in the levels of IL-2 and ESR (rs = − 0.303, p = 0.014), while IL-10 was positively related to BMI (rs = 0.261, p = 0.035)." (PMID 38240927, 2024). "ELISA analysis showed that the gout group significantly up-regulated the levels of IL-1β, Caspase-1, IL-6 and TNF-α, and significantly decreased the levels of IL-10, which were induced by MSU (p < 0.05)." (PMID 36313318, 2022). "In addition, since estrogen promotes the progression of macrophages to the IL10-dependent acquired deactivation phase and may have an anti-inflammatory effect, changes in estrogen levels may affect the onset of inflammatory diseases such as gout." (PMID 34915918, 2021). "Further PPI network analysis jointly identified three key genes, CXCL8, PTGS2, and IL10, which have a high degree of connectivity in the PPI network, suggesting that they may play a core regulatory role in the pathogenesis of gout." (PMID 40606658, 2025). "These PPI network analysis results showed that the key genes CXCL8, PTGS2 and IL10 played a key regulatory role in the PPI network, suggesting that they may play an important role in the occurrence and development of gout." (PMID 40606658, 2025). "Then, we compared cytokine levels, including IFN-γ, TNF-α, IL-2, IL-4, IL-6, IL-10 and IL-17 among gout with tophus, gout without tophus and HCs." (PMID 38240927, 2024). "Nominally significant differences were observed for 7 proteins: TRAIL (TNF-related apoptosis-inducing ligand), DNER, IL-10, and CCL3 were reduced, and IL-6, RANKL (Receptor activator of nuclear factor kappa-Β ligand), and MCP-3 were elevated in samples of patients with tophaceous gout." (PMID 37810213, 2023). "In addition, anti-inflammatory features, including CD163 expression and IL-10 production from CD14+ cells, were inhibited in RA patients more prominently compared to those with gout." (PMID 32351318, 2020). "Further, significantly higher levels of IL-10 were detected with or without stimulation in CD14+ cells from patients with gout compared to those with RA." (PMID 29056937, 2017). "In addition, anti-inflammatory features, including CD163 expression and IL-10 production from CD14+ cells, were significantly higher in patients with gout than in those with RA." (PMID 29056937, 2017). "In addition, monocytes from gout patients exhibited anti-inflammatory as well as pro-inflammatory activity, demonstrated by the production of IL-1β, IL-8, TNF-α, and IL-10." (PMID 29056937, 2017).